TNF (tumor necrosis factor)
Diseases named in the same sentence as TNF in open-access papers (continued):
Sharing a sentence is not in itself a finding about the gene and the disease.
Sepsis (continued). "Furthermore, compared with the sham group, Western blotting analysis of the collected lung tissues revealed that the expression levels of IL-6 and TNF-α proteins were increased in the model sepsis group." (PMID 36685507, 2022). "Moreover, the inflammatory cytokines of TNF-α and IL-6 were significantly higher in sepsis patients than in control (p < 0.01)." (PMID 36110326, 2022). "lncRNA HOX transcript antisense RNA (HOTAIR) overexpression in sepsis rats could reduce the IL-1β and TNF-α to improve renal function." (PMID 35464083, 2022). "In addition, considering the role of TNF in promoting ongoing deleterious inflammation in sepsis, decreased production is likely to be beneficial." (PMID 35819838, 2022). "As the concentration of inoculated E. coli increased, we observed a significant increase in serum IL-6 and TNF-α levels, indicating that adjusting the concentration of E. coli could control the severity of sepsis in our study." (PMID 36685507, 2022). "Under inflammatory conditions TNF and IL-6 demonstrate some functional redundancy: for example, they both mediate inflammatory response during sepsis, and may act as immunometabolic transmitters." (PMID 35408882, 2022). "TNF, as an endogenous pyrogen, is able to induce fever, apoptotic cell death, cachexia, and inflammation, inhibit tumorigenesis and viral replication, and respond to sepsis via IL-1 and IL-6-producing cells." (PMID 35625362, 2022). "In addition, the GSEA also suggested that TNF and NF-κB pathways were involved in sepsis, which indicated that inflammation was critically involved in sepsis." (PMID 35222395, 2022). "Sepsis is characterized by an overwhelming systemic proinflammatory response to infection and is partly attributable to a “cytokine storm”, such as IL-1β, IL-6, and TNF-α." (PMID 36064371, 2022). "Research suggests that TNF-α is another important mediator of BBB dysfunction in sepsis." (PMID 35488237, 2022). "Notably, the HLA classifier was significantly positively related to ratios of IL-10/TNF in our study, which implies that the HLA classifier can act as a promising biomarker of sepsis-induced immunoparalysis." (PMID 35685286, 2022). "Sepsis triggers the stimulation of the factors in the complement system through the secretion of inflammatory cytokines including several interleukins (IL), tumor necrosis factor α (TNFα), and nitric oxide, resulting in a systemic inflammatory response." (PMID 35317038, 2022). "Besides, in an LPS model of sepsis in vivo, we found that LPS-V not only increased IL-1β and TNF-α levels but also shortened survival compared to LPS-B did." (PMID 35523778, 2022). "Rhamnetin injection in the mouse model of sepsis downregulated TNF-α by 93.2% and IL-6 by 84.5%." (PMID 36361685, 2022). "Interestingly, TNF-α and IL-6 as cytokines involved in endothelial damage, and multiple organ dysfunction syndrome, are often used as biomarkers for sepsis." (PMID 36536294, 2022). "Mouse experiments showed that the interaction between IFN-γ and TNF-α triggers inflammatory cell death, tissue damage, and mortality in acute immune diseases characterized by a “cytokine storm,” including lipopolysaccharide (LPS)–mediated sepsis." (PMID 37395630, 2022). "These factors then drive systemic inflammation and associated septicemic pathology, with IL-6 in particular being an important driver of this response, while TNF-α additionally regulates immune cells and is produced in large quantities in the context of sepsis." (PMID 35978995, 2022). "In patients with sepsis-induced acute kidney injury, miR-107 could manipulate the production of tumor necrosis factor-α (TNF-α) in endothelial cells to induce tubular cell injury." (PMID 36180862, 2022).
Sepsis (continued). "A meta-analysis of an animal model of sepsis with resveratrol intervention suggested that resveratrol can reduce the sepsis-induced inflammatory response by reducing TNF-α, MDA, and IL-6 levels; increasing IL-10 levels; and improving mean arterial pressure, thus improving the microcirculation." (PMID 35222035, 2022). "In addition, our data also reveal calpain as a downstream target of TNF-α but are in contrast to previous studies showing that calpain triggered TNF-α expression via NF-κB activation in sepsis-induced myocardial dysfunction." (PMID 35013173, 2022). "Therefore, we assessed the gene expression of pro-inflammatory cytokines IL-1β, IL-6, TNF-α, and keratinocyte chemoattractant (KC), which are increased during sepsis." (PMID 35628471, 2022). "Using soluble TNFRSF1A to neutralize TNF reduces organ damage and mortality in sepsis rat." (PMID 36299685, 2022). "Moreover, rosiglitazone has been found to alleviate sepsis-related cardiac dysfunction and mortality by activating peroxisome proliferator-activated receptor-γ and inhibiting TNF-α expression." (PMID 35983185, 2022). "The promising result may attribute to the multimodality approach we applied in daily practice, which included MRI-guided drainage of all sepsis and early initiation of anti‐TNF agent, followed by early removal of seton." (PMID 35012467, 2022). "In our study, dual LPS injection caused lethal sepsis but not induced hippocampal or cortical TNFα responses 48 h after the last injection in aged survivor rats." (PMID 34997032, 2022). "By attenuating the release of leucocyte TNFα using a genetic murine model, we also show that leucocyte-derived TNFα is unlikely to be a major contributor to sex-specific differences in cardiac function during the critical phase of early sepsis." (PMID 35723764, 2022). "Moreover, they have been proven to induce systemic inflammatory response syndrome (SIRS) (e.g., leukopenia, thrombocytopenia, increasing the IL-6 and TNF-α concentration or sepsis)." (PMID 35283837, 2022). "This overwhelming immune response from the cytokines, including interleukin-6 (IL-6), interleukin-8 (IL-8), interleukin-1b (IL-1b), macrophage inflammatory protein-1b, and tumor necrosis factor (TNF-a) leads to sequelae of sepsis via capillary leakage and organ failure." (PMID 36004958, 2022). "Additionally, immune trained monocytes from sepsis patients upregulated TNF–α and IL–6 upon LPS stimulation." (PMID 35693816, 2022). "Furthermore, in septic patients, a high IL-10:TNF ratio equates with the clinical immunoparalytic phase and correlates with poorer sepsis outcomes." (PMID 36264059, 2022). "In contrast, isorhamnetin is known to inhibit TNF-α and IL-6 in a model of E. coli-induced sepsis." (PMID 36361685, 2022). "mTOR expression was higher in the severe sepsis than in the mild sepsis group, suggesting higher levels of lymphocyte mobilization and metabolism in patients with severe sepsis, which seemed to be confirmed by higher levels of IL and TNF-α." (PMID 35898496, 2022). "Moreover, KEGG analysis indicated that the sepsis-brown module was enriched in the TNF signaling pathway and leukocyte transendothelial migration, which substantiated the crucial role played by the immune system in sepsis." (PMID 35445133, 2022). "An in vivo model has shown that inflammatory factors such as lipopolysaccharide (LPS), tumor necrosis factor-alpha (TNF-α), and interleukin-1beta (IL-1β) are associated with sepsis and could activate CMV immediate early genes and promote viral replication." (PMID 36241980, 2022). "Using neutralizing antibodies against TNF-α can protect mice from mortality during sepsis." (PMID 36199375, 2022). "Similar to TNF-α, the crucial roles of IL-1β and IL-6 in sepsis are also established." (PMID 35337084, 2022).
Sepsis (continued). "Finally, we identified that IL-6 and TNF-α protein expression levels were significantly elevated in the sepsis group by immunohistochemistry and Western blotting analysis of renal tissues compared to the sham group." (PMID 36685507, 2022). "A negative correlation between IRAK3 and TNF-α expression in rodents following two challenges demonstrates the association of IRAK3 in the immunosuppression phase of sepsis." (PMID 35167625, 2022). "Early in sepsis, Kupffer cells play an essential role in the removal of bacteria and endotoxins through the release of proinflammatory cytokines such as interleukin (IL)-1β, IL-6, IL-18, and tumor necrosis factor-alpha (TNF-α)." (PMID 36120368, 2022). "From a mechanistic perspective, sepsis is primarily characterized by excessive inflammation response and unrestrained oxidative stress, resulting in severe inflammatory tissue damage driven by TNF-α, IL-6, and other proinflammatory cytokines." (PMID 35978995, 2022). "We speculate that inflammatory factors triggered by postnatal sepsis, such as growth factors and cytokines (IL-1, TNF-α, etc.), may modulate retinal angiogenesis and alter vessels development." (PMID 35803970, 2022). "In sepsis, circulating toxins act on the vascular endothelium, reducing microcirculation blood flow and producing a large number of inflammatory mediators, such as tumor necrosis factor and transforming growth factor β." (PMID 35035614, 2022). "When sepsis develops, inflammatory molecules such as TNF-α and IL-6 may bind to signal transducers and activators of transcription 3 (STAT3) due to early inflammation in the body." (PMID 35890197, 2022). "Similar to IL-10-stimulated cells, neutrophils stimulated by LPS or primed by TNF-α in vitro, as well as from the patients with sepsis or NMOSD, also released VEGF, but with a different pattern of chemokines (IL-8, CCL4, CCL5) and cytokines (IL-2, -5, -9, -15, -17, TNF-α) promoting inflammation." (PMID 35757755, 2022). "Finally, sepsis giving rise to fatal childhood malaria and in premature babies is also accompanied by elevated IL-1beta and TNF-alpha levels in the brain parenchyma and cerebrospinal fluid levels." (PMID 35215252, 2022). "In LPS-induced sepsis, activation of TLR4 causes downstream NF-κB and MAPKs pathways to be activated in a MyD88-dependent manner, thereby enhancing pro-inflammatory cytokines including TNF-α and IL-6." (PMID 36402943, 2022). "Furthermore, the levosimendan pretreatment reduced NO, TNF-α, IL-6, and IL-1β, as well as liver enzymes, in the serum of the sepsis rats, suggesting a hepatoprotective effect." (PMID 36551917, 2022). "At the Fluids time-point, circulating levels of pro-inflammatory cytokines (TNF-α and IL-6) had increased similarly in the two treatment groups in response to sepsis; Anti-inflammatory IL-10 levels were increased in the Ang II group at VP1 compared to baseline." (PMID 36117167, 2022). "Later, selective activation of the efferent nerve bundle in the cervical vagus nerve was demonstrated in anesthetized rats challenged with a model of sepsis and shown to be more effective at reducing systemic levels of the pro‐inflammatory cytokine TNF‐alpha than regular vagus nerve stimulation." (PMID 35439355, 2022). "This study preliminarily showed that the rs1024611 A > G polymorphism within the promoter region of MCP-1 gene can upregulate the expression of MCP-1 gene and proinflammatory cytokine TNF-α, which ultimately contributed to the predisposition and progression of T2DM with sepsis." (PMID 35960063, 2022). "A blockade of IL-6 or TNF-α was confirmed to increase the survival of patients with sepsis." (PMID 35283837, 2022). "In sepsis, the source of TNFα remains unclear, since cardiomyocytes can directly generate inflammatory mediators." (PMID 35723764, 2022).
Sepsis (continued). "The mice sepsis model is established using lipopolysaccharide (LPS) injection, and the expression levels of proinflammatory cytokines, such as tumor necrosis factor alpha (TNF-α), interleukin-6 (IL-6), and interleukin-10 (IL-10) in both RAW246.7 cells and lung tissues, are tested." (PMID 35814267, 2022). "Here, when animals with sepsis were treated with cinnamaldehyde, it was possible to observe a reduction in the levels of all cytokines in both serum and peritoneum, with the exception of TNF-α in the serum." (PMID 35326827, 2022). "In a mouse animal model, injection of IαIp modulated the immune response, and suppressed secretion of the proinflammatory cytokines such as TNF-α, improving the survival in mice models (~90%, p = 0.0159) in both live bacterial infections and with LPS-induced sepsis." (PMID 36613805, 2022). "Interestingly, 6 sites (8.3%) were correlated with age in sepsis patients, and the CpG site with the most significant correlation was in TNF-α." (PMID 35242787, 2022). "TNF-α plays a key role in sepsis occurrence and development." (PMID 35126812, 2022). "This could have been predicted from studies using murine models of CLP-induced sepsis, which also demonstrated reduced survival with the use of TNF-α inhibitors." (PMID 35648977, 2022). "Decreased tumor necrosis factor-α (TNF-α) in monocytes stimulated with endotoxin/lipopolysaccharide (LPS) is one of the main features of impaired monocyte activation, which is closely related to immunosuppression in patients with sepsis." (PMID 36567402, 2022). "Compared with the control group and the sham group, the IL-6, IL-β, INF-α protein expression of the hippocampus in the sepsis group was up-regulated (p < 0.05); After administration of the inhibitor echinomycin, the protein expression of IL-6 and TNF-α were decreased." (PMID 36569834, 2022). "In addition, we measured the mRNA levels of the inflammatory cytokine IL‐6, which is important in the pathobiology of sepsis, tumor necrosis factor alpha (TNF‐α), and the chemokine MCP‐1, at 24 h after CLP." (PMID 34355516, 2022). "Early cardiac dysfunction in experimental sepsis can be prevented by anti-TNFα therapy." (PMID 35723764, 2022). "Previous studies have shown that obeticholic acid, a derivative of chenodeoxycholic acid, can improve bile acid homeostasis; inhibit the expression of TNF-α, IL-6, and IL-1β; and alleviate sepsis-related liver injury, which suggests that bile acids have a protective effect against sepsis." (PMID 35115021, 2022). "In addition to its antioxidant effects, oxytocin also reduces the production of pro-inflammatory cytokines (such as tumor necrosis factor-alpha, interleukin-1 beta) found in sepsis models." (PMID 35572539, 2022). "This systematic review and meta-analysis showed that dexmedetomidine sedation in sepsis patients could significantly decrease mortality and IL-6 and TNF-α levels at 24 h compared with other sedatives." (PMID 36029410, 2022). "Ketamine has been applied to sepsis in macrophages stimulated with endotoxin, NF-κB, and activator protein-1 (AP-1) and affects neutrophil function and the production of inflammatory molecules such as TNF-α and interleukins." (PMID 35184141, 2022). "Monocytes from patients with sepsis, who are known to be in the state of endotoxin tolerance, produce less pro‐inflammatory cytokines, such as tumor necrosis factor‐alpha (TNF‐α), interleukin (IL)‐12, IL‐23, and IL‐6, in response to LPS stimulation, compared to monocytes from healthy volunteers." (PMID 36444621, 2022). "Additionally, we demonstrated that HRS given at early onset of sepsis induction is more effective in reducing TNF-α and IL-1β than when given at later time point, though more studies are needed to validate this effect." (PMID 36435787, 2022).
Sepsis (continued). "Endotoxin tolerance of peripheral blood mononuclear cells (PBMCs) and splenocytes was also investigated to determine the level of immune suppression 24 h after sepsis by measuring TNF-α production after stimulation with lipopolysaccharide (LPS) in an ex vivo model." (PMID 35330172, 2022). "We detected the expression levels of TNF-α, IL-1β, IL-6, and IL-10 in sera and BALF of septic mice using ELISA, and the results indicated that Fer-1 reduced the upregulation of the expression levels of inflammatory factors caused by sepsis in mice (P < 0.05)." (PMID 35910848, 2022). "The study found that the main components of XBJ in the treatment of sepsis-induced cardiac dysfunction are paeoniflorin and hydroxysafflor yellow A, and its potential target may be related to NF-κB, TNF-α, and CXCL2." (PMID 36188532, 2022). "Furthermore, blocking both IFN-γ and TNF-α with specific antibodies protected against inflammatory cell death and animal mortality from cytokine shock, sepsis, and hemophagocytic lymphohistiocytosis, in addition to SARS-CoV-2 infection." (PMID 36203588, 2022). "They hypothesized, that at the time of sample collection, the inflammatory response in cases of congenital sepsis had already progressed past the rapidly peaking TNF secretion." (PMID 35345614, 2022). "Cepharanthine, an alkaloid isolated from Stephania cepharantha Hayata, demonstrated effectiveness in managing systemic inflammatory response syndromes including sepsis by inhibiting the rise in LPS-induced cytokine levels (IL-6, TNF-α, and nitrate/nitrite levels) in rat serum." (PMID 36588685, 2022). "The serum levels of TNF-α increased significantly (p < 0.05) following the induction of sepsis." (PMID 35884918, 2022). "It concludes that the accentuated levels of TNF-alpha and IL-6 may be the inciting agent for the hepatocellular dysregulation in the early stage of sepsis." (PMID 35282512, 2022). "miR-107 is highly-expressed in the whole blood of mice with LPS-induced sepsis, and miR-107 could induce TNF-α secretion in endothelial cells and thus result in tubular cell injury." (PMID 36180862, 2022). "Furthermore, sepsis led to a significant increase in plasma and myocardial levels of pro-inflammatory factors, such as TNF-α and IL-1β, compared with those in the control group, whereas the EA pre-treatment reduced inflammation compared with the LPS group." (PMID 36160853, 2022). "It has been previously reported that CQ could protect against liver damage in sepsis-induced acute kidney injury by suppressing the expression of the inflammatory cytokines TNF-α and IL-10 through TLR9 inhibition." (PMID 35346242, 2022). "Also, it significantly decreased MDA (p < 0.001), TNF-α (p < 0.001), and lactate levels in rats induced by sepsis." (PMID 36082333, 2022). "Reduced TNF-α with MEDI3622 treatment was also shown in the sepsis model." (PMID 35757773, 2022). "We therefore examined whether there are sex-specific differences in cardiac function in early sepsis, controlling for volaemic status and sex-specific differences in the peripheral inflammatory response initiated by tumour necrosis factor (TNFα)." (PMID 35723764, 2022). "Interestingly, animal models of sepsis have demonstrated that glycocalyx degradation involved the activation of endothelial heparanase, via TNF-α-dependent mechanisms." (PMID 35347344, 2022). "In these experiments, the TNF response to LPS could be rescued by first pharmacologically blocking the CAP pathway, demonstrating that suppression of the LPS-triggered TNF response in sepsis survivors was likely due to constitutive vagus nerve activation." (PMID 35784337, 2022). "FTB treatment lowered the levels of CRP, IL-6, IL-1β, and TNF-α in rats with sepsis." (PMID 36408247, 2022). "However, NK cells will become tolerant and cytokine production of IFN-γ and TNF-α will be impaired in the late stage of sepsis." (PMID 36532037, 2022).